SLC3A2 (solute carrier family 3 member 2)
Diseases named in the same sentence as SLC3A2 in open-access papers (continued):
Sharing a sentence is not in itself a finding about the gene and the disease.
tumor (continued). "Analysis of the expression of geneset associated with T- and B-cell activation in HNSCC revealed that it negatively correlates with SLC3A2 (CD98hc) expression, and therefore, CD98hc could be potentially associated with tumor immune evasion." (PMID 37823053, 2023). "Moreover, we also found that SLC3A2 was negatively associated with the M1 signature, which was also an essential player in anti-tumor immunity." (PMID 35992269, 2022). "This indicates that residual SLC7A5 activity may allow normal cell function in SLC3A2-deficient tumor cells." (PMID 33953707, 2021). "In addition, hallmark analysis of DEGs showed that SLC3A2+ Tfh tumor cells were particularly enriched in pathways closely associated with cell proliferation, inflammatory responses, and oxidative phosphorylation, indicating that SLC3A2 expression is related to AITL progression." (PMID 40344476, 2025). "In addition, the CNVs of SLC7A11, and SLC3A2 were negatively linked with their expression in most tumor types, while the CNVs other disulfidptosis genes were positively linked with their expression, uncovering that the CNVs contributed to abnormal expression of the disulfidptosis genes." (PMID 39605832, 2024). "Moreover, we demonstrated that SLC3A2 deficiency decreases tumor growth in vivo." (PMID 35057861, 2022). "In addition, high SLC3A2 protein was associated with medullary-like tumours (p < 0.001)." (PMID 29545595, 2018). "IFN‐β can reduce the expression of SLC7A11 and SLC3A2 on the tumor cell membrane, disrupt the tumor cell's antioxidant system, and induce tumor cell ferroptosis." (PMID 41560416, 2026). "Mechanistically, SPARCL1 appears to mediate its anti-tumor effects through the SLC3A2-mediated ferroptosis pathway, suggesting a novel mechanism by which SPARCL1 influences PTC progression." (PMID 42160309, 2026). "Collectively, these results suggest that arginine uptake is overly active in PTCL tumor cells and that SLC3A2, a putative arginine transporter, is highly expressed in patients with PTCL and predicts poor prognosis." (PMID 40344476, 2025). "IFNγ operates through a cysteine/glutamic acid reverse transport system, solute carrier family 7 member 11(SLC7A11) and SLC3A2, that targets the surface of tumor cell membranes." (PMID 39820341, 2025). "More importantly, among patients receiving endocrine therapy alone, those with SLC7A5+/SLC3A2+ tumours experienced poorer prognosis, higher recurrence and mortality rates." (PMID 41154605, 2025). "Further analysis of clinical relevance revealed that high SLC3A2 expression was positively correlated with tumor size and lymph node metastasis." (PMID 40695795, 2025). "SLC3A2 is a molecular chaperon of light chain subunits, capable of regulating amino acid transport, leading to an important role in tumor growth and oxidative stress control." (PMID 40136510, 2025). "Multicolor immunofluorescence analyses of AITL samples revealed that SLC3A2 expression in tumor cells was inversely correlated with granzyme B+CD8+ T‐cell infiltration." (PMID 40344476, 2025). "We demonstrated that quinacrine treatment downregulated the intracellular arginine pool by targeting SLC3A2 and selectively inhibiting tumor growth." (PMID 40344476, 2025). "SLC3A2 was significantly overexpressed in CRC tissues based on IHC staining and associated with enhanced tumour growth and metastasis." (PMID 41154605, 2025). "The role of SLC3A2 in immune evasion and tumor progression highlights its potential as a therapeutic target." (PMID 40362545, 2025). "Inhibition of the anti-ferroptosis factor SLC7A11/SLC3A2 upregulates PD-L1 expression in tumor cells via IRF4/EGR1." (PMID 41373022, 2025). "Secondly, we analyzed immunohistochemistry data from the Human Protein Atlas database, which indicated that SLC3A2 is predominantly localized on tumor cell membranes." (PMID 39926285, 2025).
tumor (continued). "Single‐cell transcriptomic analyses reveal aberrant arginine metabolism in patients with PTCL, characterized by excessive solute carrier family 3 member 2 (SLC3A2) mediated arginine uptake preferentially in tumor cells." (PMID 40344476, 2025). "In accordance with cell experiment results, lower protein levels of GPX4, p-Stat3, Stat3, SLC7A11 and SLC3A2 were found in nude mice tumor tissues from UA (40 mg/kg) group." (PMID 41341590, 2025). "Activated CTLs secrete IFN-γ, which downregulates tumor SLC7A11 and SLC3A2 (components of system Xc−), thereby sensitizing tumor cells to ferroptosis." (PMID 41301464, 2025). "The SLC3A2 gene is important for disulfide production and metabolism and affects tumor invasiveness; overexpression of SLC3A2 led to decreased expression of PD-1 and CTLA-4 in SCC-9 cells." (PMID 40362545, 2025). "Among these, SLC1A5 (also known as ASCT2), SLC7A5 (LAT1) and its heavy chain SLC3A2 (CD98hc), and SLC38A1 (SNAT1) are highly expressed in various cancers and have been implicated in tumor progression, therapeutic resistance and clinical outcome." (PMID 40707944, 2025). "Among these, ASCT2, GLS1, LAT1, SLC7A11, SLC3A2, and SHMT2 are key regulators of amino acid metabolism and have been implicated in tumour progression, therapy resistance, and immune evasion." (PMID 41154605, 2025). "IFNγ produced by CD8+ T cells triggers the JAK/STAT1 pathway, downregulating SLC7A11 and SLC3A2, which makes tumor cells more vulnerable to ferroptosis." (PMID 40136510, 2025). "Beyond nutrient transport, SLC3A2 is involved in integrin signaling and cell adhesion, further enhancing its role in metastasis, tumor microenvironment remodeling, and promoting tumorigenesis." (PMID 40566559, 2025). "Despite its pivotal role in tumor biology, SLC3A2 remains underexplored as a therapeutic target, particularly in the context of natural compound-based interventions." (PMID 40566559, 2025). "SLC3A2 is a neutral amino acid transporter that interacts with other transporters and supports amino acid uptake and tumor growth in cancer." (PMID 40362545, 2025). "Understanding how SLC3A2 impacts the immune dynamics within the tumor microenvironment is crucial for our future studies." (PMID 38977800, 2024). "More importantly, this study also revealed that deletion of SLC3A2 after tumor induction leads to tumor regression." (PMID 38705513, 2024). "In this comprehensive survey, we meticulously studied the impact of the SLC3A2 gene on the tumor microenvironment from multiple perspectives." (PMID 38977800, 2024). "This study has successfully established the role of SLC3A2 in modulating immune infiltration and its impact on tumor proliferation, metastasis, and invasion." (PMID 38977800, 2024). "Short-term acidosis can induce M1 macrophage polarization to promote tumor cell ferroptosis via the ZFAND5/SLC3A2 signaling axis in breast cancer." (PMID 39614322, 2024). "IFN-γ released by CD8+ T cells down-regulates the expression of two subunits of system Xc-, SLC3A2 and SLC7A11, inhibits the uptake of cystine by tumor cells, enhances lipid peroxidation, causes ferroptosis of tumor cells, and releases DAMP." (PMID 39359721, 2024). "Immunohistochemistry for SLC7A11, SLC3A2, and PD-L1 will be performed on tumor tissues from ISMC patients to preliminarily explore potential therapeutic targets for ISMC." (PMID 39807126, 2024). "For example, CD8+ T cells suppress the expression of SLC7A11 and SLC3A2 in tumor cells via IFNγ release, increasing tumor cell sensitivity to ferroptosis." (PMID 39273090, 2024). "Nevertheless, there are limitations to our study: the experimental part of this study has not been extended to explore the mechanism of coordination between SLC3A2 and tumor immune infiltration." (PMID 38977800, 2024). "Tumor immunotherapy studies have shown that interferons released from CD8 + T cells can downregulate SLC3A2 and promote tumor cell ferroptosis." (PMID 38438962, 2024).
tumor (continued). "In vivo, knockdown of SLC3A2 led to a reduction in tumor volume and prolonged survival in tumor-bearing mice." (PMID 38977800, 2024). "These analyses illuminated a marked ascendancy in SLC3A2 mRNA within tumor specimens relative to normal tissues (P < 0.001 for all datasets)." (PMID 38977800, 2024). "Upregulated SLC3A2 influenced the tumor microenvironment by altering immune cell infiltration, particularly of macrophages, and tumor migration and invasion." (PMID 38977800, 2024). "Findings indicated a substantial reduction in tumor sizes and an improvement in the survival rates of mice in the SLC3A2 knockdown group over 30 days, compared to the control group." (PMID 38977800, 2024). "Increasing evidence has shown that the transport of amino acids through SLC3A2 plays an important role in the occurrence and progression of tumours." (PMID 37829798, 2023). "Simultaneously, in lung cancer, SLC3A2 can induce tumour occurrence and metastasis through the MEK/ERK signalling pathway so that it can be used as a prognostic marker, and its serum content can be used to evaluate patient prognosis." (PMID 37829798, 2023). "It was also recently determined that CTLs secrete IFNγ to activate the STAT1-IRF1 axis, in order to repress the expression of SLC7A11 and SLC3A2 to induce the extrinsic ferroptosis pathway in tumor cells." (PMID 36672246, 2023). "In summary, SLC3A2, the partner subunit of xCT, plays an important role in protecting against oxidative stress and promoting tumour cell proliferation and metastasis." (PMID 37829798, 2023). "The alterations in SLC3A2 and FKBP1A genes both contributed a significant impact on BC tumor mutational burden." (PMID 37484811, 2023). "It has been discovered that SLC3A2 plays a crucial role in tumour occurrence and development by participating in glycine transport and regulating extracellular matrix structure." (PMID 37927242, 2023). "In this regard, SLC3A2 is significantly upregulated in several types of malignant tumor cells, including those of the lung, breast, and prostate." (PMID 37799714, 2023). "Taken together, these results indicated that knockdown of SLC3A2 contributes to PDAC tumor suppression and this antitumor activity can be largely enhanced by combination with IKE or TM." (PMID 37479744, 2023). "STAT1 then upregulates IRF1 to repress the expression of SLC7A11 and SLC3A2, the two subunits of the glutamate-cystine antiporter system xc-, to limit tumor cell cystine uptake, resulting in tumor cell lipid peroxidation and death." (PMID 36672246, 2023). "Many types of cancer cells have an elevated expression of SLC7A11 and SLC3A2, a feature benefiting L-Cystine uptake and high metabolic activity for tumor growth." (PMID 36672226, 2023). "SLC3A2 modulates the levels of peroxides in the tumour microenvironment, thereby influencing the formation and dissociation of intracellular disulphide bonds." (PMID 37927242, 2023). "In summary, decreased expression of SLC3A2 in OSCC can induce immune escape of tumour cells by inhibiting the immune function of T lymphocytes, thereby accelerating the progression of OSCC." (PMID 37927242, 2023). "In a study of colorectal cancer, knockdown of MIF and SLC3A2 promoted cell iron-related death and inhibited tumour growth and metastasis via the AKT/GSK-3β pathway." (PMID 37829798, 2023). "A study on tumor immunotherapy found that interferon released by CD8+ T cells can downregulate the expression of SLC3A2 to promote tumor cell ferroptosis." (PMID 36359826, 2022).
tumor (continued). "IFN γ released from immunotherapy-actived CD8+ T promotes ferroptosis in tumor cells by decreasing the expression of SLC3A2 and SLC7A11, which is instrumental in boosting the efficacy of cancer immunotherapy." (PMID 35309911, 2022). "Further, the inhibition of SLC3A2, a ferroptosis suppressor gene, promotes ferroptosis in tumor and normal cells, and hence, its upregulation is associated with poor prognosis of cancer." (PMID 35345408, 2022). "Slc3a2 plays important roles in tumor growth and oxidative stress control (Digomann, Linge & Dubrovska, 2019)." (PMID 35923893, 2022). "Zhu and colleagues reported that SLC3A2 was highly expressed in human osteosarcoma and facilitated tumor growth via the PI3K/Akt signaling pathway." (PMID 35057861, 2022). "This nutrient limitation would trigger GCN2 induction of the ISR which features induced expression of SLC transporters, including the central 4F2 (SLC3A2), and these events are required to sustain tumor growth." (PMID 36107759, 2022). "Genes blocking ferroptosis were upregulated (e.g., Slc40a1, Slc7a11, Slc3a2, and Gpx4) in Tyro3-OE 4T1 tumor cells, whereas genes that induced or enhanced ferroptosis were downregulated (e.g., Slc5a1 and Tfrc), compared with levels in 4T1-P cells." (PMID 35399527, 2022). "Subsequent western blotting analysis showed that IFN-γ markedly reduced tumor cells’ SLC3A2 and SLC7A11 protein expression with increased IRF1 expression, which indicated the possible involvement of the JAK/STAT1 signaling pathway." (PMID 35399527, 2022). "SLC3A2 has been shown to be associated with radiotherapy resistance in many tumors, and overexpression of SLC3A2 leads to worse prognosis by promoting tumor development and reducing apoptosis." (PMID 35232428, 2022). "(I) Tumor growth curves for 22Rv1 WT or 22Rv1 GCN2 KO (clone 11) transduced with 4F2 (SLC3A2) lentivirus (WT + 4F2 and GCN2 KO + 4F2) or empty vector (WT + EV and GCN2 KO + EV)." (PMID 36107759, 2022). "The IFNγ secreted by CD8+ T cells downregulates the expression of SLC7A11 and SLC3A2, and therefore attenuates the uptake of cystine by tumor cells, consequently enhancing lipid peroxidation in tumor cells, ultimately increasing ferroptosis." (PMID 35531466, 2022). "Several studies have found that SLC3A2 is overexpressed in many tumours and participates in the malignant transformation of cells." (PMID 35567291, 2022). "We found that inhibition of MIF or SLC3A2 expression in vivo markedly suppressed the growth of tumours, and the inhibitory effect was even more significant in the co‐transfection group." (PMID 35567291, 2022). "Another study noted that CD8+ T cells suppress cystine uptake by tumor cells through down-regulation of SLC3A2 and SLC7A11 expression and promote ferroptosis and lipid peroxidation in tumor cells." (PMID 36776357, 2022). "Studies have shown that inhibition of XCT and SLC3A2 expression can promote tumor cell lipid peroxidation and ferroptosis." (PMID 35958925, 2022). "Due to the lack of normal samples in the TCGA cohort, we first integrated tumor samples in TCGA and normal tissues in the GTEx database, which made it more reliable to explore the differential expression of SLC3A2." (PMID 35992269, 2022). "Further experiments showed that knockdown of MIF and SLC3A2 inhibited tumour growth and metastasis by promoting iron death and regulating the AKT/GSK‐3β pathway in vivo." (PMID 35567291, 2022). "Few molecular mechanisms by which SLC3A2 regulates anti-tumor immunity have been clarified in the present study, which is the main limitation." (PMID 35992269, 2022). "In immunotherapy, activated CD8+ T cells enhanced ferroptosis‐mediated lipid peroxidation in tumor cells by downregulating the expression of SLC7A11and SLC3A2 through the release of γ‐IFN." (PMID 35373463, 2022). "More importantly, inhibition of either MIF or SLC3A2 in vivo significantly promoted the apoptosis of tumour cells, and especially in cells co‐transfected with shMIF and shSLC3A2." (PMID 35567291, 2022).
tumor (continued). "While three genes (AHNAK, ABCC9, and DIP2C) were highly expressed in normal tissues, eight genes (CHMP4C, CLIC3, DARS2, PLOD1, POU5F1, RAD9A, RUNX2, SLC3A2) were highly expressed in tumour tissues." (PMID 36685927, 2022). "Knockdown of both MIF and SLC3A2 inhibited tumour growth and metastasis via the AKT/GSK‐3β pathway in vivo." (PMID 35567291, 2022). "SLC3A2-specific CAR T cells demonstrated cytotoxicity against tumor cells, stimulated interferon-γ and interleukin-2 production in vitro." (PMID 34112739, 2021). "The levels of CD98hc/SLC3A2 and its light chain subunits are upregulated in tumors, and its high expression is associated with tumor progression and treatment resistance." (PMID 33401748, 2021). "After tumor immunotherapy, IFNγ released by activated CD8 + T cells downregulates the expression of SLC7A11 and SLC3A2, thereby inhibiting the uptake of cystine in tumor cells and enhancing LPO and ferroptosis." (PMID 34630843, 2021). "Upregulated expression of SLC7A11 (10/14), SLC1A5 (7/14), SLC7A5 (6/14), and SLC3A2 (5/14) was observed in most of the tumor tissues; however, GLS in LUSC, KIRC, and KICH and GLS2 in KIRC and LIHC, were significantly downregulated." (PMID 34573287, 2021). "In our study, ASCT2 and SLC3A2 were consistently upregulated in tumour cell lines that exhibited prolonged survival following plasma treatment." (PMID 33767419, 2021). "IFN-γ can downregulate the expression of two subunits of the glutamate-cystine antiporter on the surface of tumor cells, namely, solute carrier family 3 member 2 (SLC3A2) and SLC7A11, thereby inhibiting tumors." (PMID 34335679, 2021). "Intriguingly, IFNγ released from CD8+ T cells downregulates the expression of SLC7A11 and SLC3A2, thereby limiting cystine uptake by tumor cells and promoting tumor cell lipid peroxidation and ferroptosis." (PMID 34312372, 2021). "SLC7A11 and SLC3A2 are highly expressed in tumor cell lines and increase cellular antioxidant capacity." (PMID 34630843, 2021). "Results were consistent with SLC7A5/SLC3A2 mRNA expression whereby patients with SLC7A5+SLC3A2+ tumours had a worse outcome compared to patients of other subgroups." (PMID 32093034, 2020). "SLC7A5 functions in supplying amino acids to cancer cells as well as maintaining intra-cellular leucine, and SLC3A2 is required for the functional expression of SLC7A5 in tumour cells." (PMID 32093034, 2020). "SLC3A2 mRNA and protein expression were strongly correlated with higher tumour grade and poor Nottingham prognostic index (NPI)." (PMID 29545595, 2018). "Regarding the ER+ BC subtypes, SLC3A2 expression was lower in ER+ tumours that have low proliferation compared with the highly proliferative ER+ tumours, and it was associated with poor patient outcome in the latter class only." (PMID 29545595, 2018). "Expression of SLC3A2 protein in the defined molecular subtypes showed a lower expression in the ER+ low-proliferation tumours compared with the other subtypes (p < 0.001)." (PMID 29545595, 2018). "Quantitative PCR analysis of the human specific Alu sequence also demonstrated that the intravasated tumor cells into the lung tissues of chick embryo were significantly increased to 1.6 fold in SLC3A2 overexpression group." (PMID 29179459, 2017). "SLC3A2 expression was upregulated in GC tumor tissues compared with normal tissues (P < 0.05, Wilcoxon test)." (PMID 29179459, 2017). "Next, CAM assay indicated that tumor growth of BGC-823 cells on CAM was significantly reduced after knockout of SLC3A2, compared to control cells transfected with GFP gRNA." (PMID 29179459, 2017). "Consistent to this result, we also found the expression of SLC3A2 was elevated in GC tumor tissues, and increased expression SLC3A2 was significantly associated with serosal invasion and marginally associated with lymphonode metastasis in GC patients." (PMID 29179459, 2017).